HDAC3 (histone deacetylase 3)
Diseases named in the same sentence as HDAC3 in open-access papers (continued):
Sharing a sentence is not in itself a finding about the gene and the disease.
tumor (continued). "Here, we have summarized the latest research on HDAC3 regulation of anti-tumor immunity to highlight the importance of HDAC3 as a therapeutic target for sensitizing tumor immunotherapy and its relevance in this research field, thereby encouraging more attention and investment in this area." (PMID 40006729, 2025). "Therefore, the combination of HDAC3 regulators with immunotherapy is proposed as an innovative tumor treatment strategy with significant clinical potential and research prospects." (PMID 40006729, 2025). "It is reasonable to propose that overexpressing HDAC3 may enhance the expression of various cell-surface immune checkpoints within the tumor microenvironment (TME)." (PMID 40006729, 2025). "However, HDAC3 mediates immune evasion in tumor cells by interacting with the transcription factor SP3, which inhibits ULBP1 protein expression." (PMID 40006729, 2025). "Additionally, PDCD5 has been shown to facilitate the degradation of histone deacetylase HDAC3 in tumor cells and endothelial cells." (PMID 40111008, 2025). "Additionally, IκBζ suppresses Cxcl9, Cxcl10, and Ccl5 expression via HDAC3 and EZH2, which impairs the recruitment of NK and CD8+ T cells into the tumor, causing resistance to α-PD-1 immunotherapy in mice." (PMID 40562773, 2025). "Furthermore, HDAC3, as a part of the NCoR repressor complex, can suppress the expression of Cxcl10 and Ccl5 in several tumor entities, leading to T-cell and NK-cell exclusion from the TME and immunotherapy resistance." (PMID 40562773, 2025). "Research on HDAC3 inhibitors as sensitizers for tumor treatment has been reported." (PMID 40006729, 2025). "HDAC3 can modulate the activity of T cells and macrophages, impacting their anti-tumor functions." (PMID 40006729, 2025). "Third, metabolic rewiring and tumor microenvironmental cues such as hypoxia or immune infiltration may modulate ferroptosis sensitivity downstream of HDAC3." (PMID 40947430, 2025). "USP38, through its deubiquitinating activity, removes the K63 polyubiquitin chain at the K121 site of HDAC3, enhancing HDAC3’s deacetylation of H3K27 in the promoter regions of tumor stemness-related genes, thereby effectively regulating tumor stem cell properties." (PMID 40936898, 2025). "Given HDAC3’s broader functions in chromatin remodeling and tumor progression, this approach may also be applicable to other HDAC3-driven malignancies." (PMID 40947430, 2025). "Furthermore, RMS cell lines are among the most dependent on HDAC3 expression among all the tumor cell lines present in the DepMap portal, confirming the importance of HDAC3 in RMS cells survival." (PMID 39107280, 2024). "However, HDAC3 loss-of-function radiosensitizes FP-RMS cells in vivo, allowing IR to maintain more efficiently low the tumor growth in tumors HDAC3-depleted when compared to HDAC3 KO alone." (PMID 39107280, 2024). "Furthermore, RMS cell lines resulted one of the most HDAC3-dependent tumor cell lines among several other tumor cell types." (PMID 39107280, 2024). "Thus, we focused on the development of a new chemical entity designed to selectively inhibit HDAC3, with the aim to mitigate toxicity maintaining unaltered the anti-tumor effectiveness." (PMID 39107280, 2024). "Considering these promising results, we have developed MC4448, a novel highly tumor-selective HDAC3-specific inhibitor, active towards HDAC3 at submicromolar level and displaying 3 to 5 magnitude orders selectivity for HDAC3 respect to the other tested HDAC isoforms." (PMID 39107280, 2024). "Finally, HDAC3 depletion per se impairs tumor growth and amplifies the growth inhibitory effects of IR in vivo." (PMID 39107280, 2024). "Moreover, HDAC3 depletion hampers FP-RMS tumor growth in vivo and maximally inhibits the growth of irradiated tumors compared to single approaches." (PMID 39107280, 2024).
tumor (continued). "Furthermore, HDAC2 and HDAC3 are strongly expressed in tumor subgroups with more aggressive features, such as less differentiated tumors and negative hormone receptor status." (PMID 38935814, 2024). "HPA and RT-qPCR analysis of whether they are aberrantly expressed in OSCC showed that SIRT5 and HDAC3 were significantly upregulated in tumor tissues when compared with normal samples." (PMID 37705968, 2023). "In addition, the identification of the FDA-approved druggable target (HDAC3) and the four immune checkpoint molecules in BM suggest that targeted therapies should be tailored for specific tumor lineages in order to effectively manage brain metastasis." (PMID 38149244, 2023). "HDAC3 initiates tumor activity by regulating the FOXA2-mediated FTO/m6A/MYC axis." (PMID 37932821, 2023). "This indicates that HDAC3 may have a more general tumor-suppressive role in keeping c-MYC target genes at bay." (PMID 36846090, 2022). "Silencing of HDAC3 inhibited tumor growth of ESCC in vivo via the MiR-494/TGIF1/TGFβ axis." (PMID 35578338, 2022). "Therefore, change of chromosomal modifications in PDFS cells by HDAC3 inhibition and DNA demethylation led to activation of multiple tumor suppressors, resulting in growth suppression." (PMID 35646715, 2022). "Additionally, CDM inhibited tumor growth in vivo via HDAC3 downregulation and FOXO1 acetylation induction." (PMID 35126526, 2022). "HDAC3 expression modulated tumor formation in xenograft experiments." (PMID 34991620, 2022). "However, tumor progression is a complex pathophysiological process, and HDAC3 alone cannot control biological behavior." (PMID 34991620, 2022). "Experiments in xenografts confirmed that HDAC3 mediated tumor formation." (PMID 34991620, 2022). "In addition, the results of Western blotting suggested a decline in HDAC3 expression in the tumor tissues of CDM-H-treated mice, while FOXO1 acetylation level was increased." (PMID 35126526, 2022). "Interestingly, we found that entinostat (target of HDAC1/HDAC3) acts as a tumor suppressor and a pro-apoptosis and cell cycle-blocking drug and acts on HCCLM3 and Huh-7 (concentrations of 0, 5, and 10 μM)." (PMID 36263167, 2022). "Furthermore, HDAC-1, HDAC-2 and HDAC-3 expression levels were positively correlated with tumor proliferative status, assessed as Ki67 labeling index." (PMID 34441281, 2021). "In addition, we found that PD-L1 expression was decreased in stable tumor-isolated A549/CDDPHDAC3 cells with high HDAC3 expression compared with tumor-isolated control cells (A549/CDDPpReceiver cells)." (PMID 32024543, 2020). "Finally, we show that HDAC3 KO in BMSC impairs tumor engraftment and growth in a murine xenograft model of human MM, further supporting the potential clinical utility of HDAC3 inhibition to target MM cells in the context of the BM niche." (PMID 31142847, 2020). "It prevented antigen from inducing interactions of FcεRIβ with HDAC3 and Lyn in tumor tissues." (PMID 31024564, 2019). "The upregulated expression of HDAC3 in human HCC prompts us to determine whether the HDAC3–STAT3 pathway enhances HCC tumor growth." (PMID 29540666, 2018). "We performed immunohistochemistry to assess HDAC3 expression in tissues from 90 HCC cases, and observed that 27 cases exhibited strong nuclear and cytoplasmic HDAC3 positivity, and that HDAC3 was either negatively or weakly expressed in the corresponding adjacent non-tumor tissues." (PMID 29540666, 2018). "Furthermore, HDAC3 is a considered biomarker of tumor recurrence following liver transplantation in hepatitis B virus-associated HCC13." (PMID 29540666, 2018). "MS275 is a selective HDAC1 and HDAC3 inhibitor, it has multiple anti-tumor effects." (PMID 30547810, 2018). "HDAC2 and HDAC3 are strongly expressed in more aggressive tumor subtypes." (PMID 23627572, 2013).
tumor (continued). "These independent observations in tumor cells underscore the fact that over expression of HDAC3 can lead to cellular effects that affect cell growth, proliferation and the expression signaling proteins that regulate the function of key cytokines involved in innate immunity." (PMID 21346816, 2011). "Especially the absence of HDAC3 in the most common histological variant of RCC (clear cell RCC) suggests different regulatory mechanisms of the three isoforms in this tumour entity." (PMID 19099586, 2008). "Therefore, the use of HDAC3 inhibitors can effectively enhance anti-tumor immune responses." (PMID 40006729, 2025). "Moreover, tumor volumes of irradiated sgHDAC3 mice showed greater reduction in comparison with non-irradiated sgHDAC3 and irradiate control mice by further 45% and 58% respectively suggesting additive effects of HDAC3 depletion and IR on tumor growth in vivo." (PMID 39107280, 2024). "However, the epigenomic elements regulated by HDAC3 in this tumor context are still unknown, and we should also consider the contributions of HDAC3 as a partner of ERs." (PMID 39624079, 2024). "Finally, we sought to investigate whether the anti-tumor effect of CDM in vivo was correlated with the regulation of the HDAC3/FOXO1 axis." (PMID 35126526, 2022). "Furthermore, immunohistochemistry and HE staining showed that the expression of Ki67 and tumor cells in nude mice were diminished in the presence of sh-HDAC3, the results of which could be reversed by further oe-TGIF1 treatment." (PMID 35578338, 2022). "Additionally, high expression of HDAC3 correlates with a low expression of miR-376-3p and high expression of WNT2b, and strong HDAC3 expression is associated with tumor grade, tumor infiltration depth, LNM, and tumor stage in GC." (PMID 36358890, 2022). "However, the subcellular localization of HDAC3 varied in tumor cells and could be in the nucleus, cytoplasm, or both." (PMID 32686908, 2020). "To determine whether inhibition of a specific HDAC3 target of ENT was responsible for cytoreduction in eRMS, we performed CRISPR-Cas9-mediated targeting of the deacetylase domains of HDAC3 in the U57810 murine eRMS primary tumor cell culture which were then tracked for cell viability over 16 days." (PMID 31113472, 2019). "Importantly, HDAC3 inhibition, but not HDAC1 or 2, significantly augmented BTZ-induced cytotoxicity in vitro, and triggered tumor growth inhibition in a murine xenograft model of human MM, suggesting that HDAC3 represents a promising therapeutic target for the treatment of MM." (PMID 28203307, 2017). "Our finding that HDAC3 functions cooperatively with the Brm complex in suppressing suppressing dedifferentiation of INPs into neuroblasts and induces tumors in the allograph transplantation revealed an unexpected potential involvement of HDAC3 in tumor suppression in brain tissue." (PMID 24618901, 2014). "Indeed, we provide support for the notion that both HDACi and MTM promote neuroprotection by inhibiting the expression or functions of proteins that mediate transformation such as Myc, HDAC1, HDAC2 and HDAC3 and by promoting the expression of tumor suppressors such as p21waf1/cip1." (PMID 22582024, 2011). "The overexpression of HDAC1, HDAC2, HDAC3, and HDAC6, together with aberrant DNA methylation, contributes to tumor suppressor gene silencing." (PMID 41562705, 2026). "For instance, in a xenograft tumor mouse model constructed using A549/CDDP cells, overexpression of HDAC3 and inhibition of the JNK/c-Jun signaling pathway effectively suppressed PD-L1 expression and reduced chemoresistance in tumor cells." (PMID 40006729, 2025). "Trichostatin A, an HDAC3 inhibitor, has been shown to effectively upregulate the expression of ULBP ligands in tumor cells, thereby activating NK cell-mediated anti-tumor immunity." (PMID 40006729, 2025).
tumor (continued). "Therefore, silencing HDAC3 or using HDAC3 inhibitors may facilitate the synthesis and normal function of retinoic acid, thereby exerting beneficial effects on maintaining and enhancing anti-tumor immune responses." (PMID 40006729, 2025). "It serves as an E3 ligase for histone deacetylase 3 (HDAC3), forkhead box O4 (FOXO4), and insulin-like growth factor 1 receptor (IGF-1R), affecting cellular migration, metabolic adaptation, and tumor growth." (PMID 41170373, 2025). "When HDAC3 is blocked, it slows the growth of MCA205 tumors and draws more CXCR3+ T-cells into the tumor environment." (PMID 40006729, 2025). "Chidamide inhibits the activity of HDAC3, HDAC1, HDAC3, and HDAC10 selectively, suppressing tumor cell proliferation and triggers tumor cell apoptosis effectively." (PMID 40963853, 2025). "To disrupt these interactions, we designed novel decoy peptides that potentially competes with both HDAC3 and NME2, effectively inhibiting PIWIL2-driven tumor activity in Huh7, HepG2, SNU449, and SNU398 HCC cell lines." (PMID 41422314, 2025). "However, after a period of low tumor growth for those HDAC3 KO established tumors, they appear to regrowth suggesting that HDAC3 expression per se could be essential particularly for the in vivo engraftment and the first phases of tumor growth." (PMID 39107280, 2024). "In our comprehensive analysis of HDACs in DLBCL patients using public databases, we found that the expression levels of HDAC1, HDAC2, HDAC3, HDAC6, HDAC7, HDAC8, and HDAC9 were higher in tumor tissues compared to normal control for the first time." (PMID 38168914, 2024). "We, then, developed a new HDAC3 inhibitor, MC4448, which showed specific cell anti-tumor effects and mirrors the radiosensitizing effects of HDAC3 depletion in vitro synergizing with ERKs inhibition." (PMID 39107280, 2024). "Overall, our findings dissect the pro-survival role of HDAC3 in FP-RMS and suggest HDAC3 genetic or pharmacologic inhibition as a new promising strategy to overcome radioresistance in this tumor." (PMID 39107280, 2024). "SFMBT2 exerted an anti-tumor role in clear cell RCC cells, and HDAC3-mediated deacetylation promoted SIAH1-controlled ubiquitination of SFMBT2." (PMID 38734627, 2024). "Altogether, these data demonstrated that the HDAC3 depletion radiosensitize FP-RMS cells strongly reducing their tumorigenic features in vitro and impairing tumor growth in vivo." (PMID 39107280, 2024). "At molecular level, LINC00355 interacts with histone deacetylase 3 (HDAC3) to suppress the transcriptional activity of tumor protein-induced nuclear protein 1 (TP53INP1), a stress-responsive protein with tumor-suppressor function." (PMID 37670949, 2023). "HDAC3 has been documented to be highly expressed in ESCC cells, playing a promoting role in tumor progression." (PMID 35578338, 2022). "HDAC3: Compared to HDAC1 or 2, even far less is known about the expression of the third member of the class I HDACs namely HDAC3 and its role in tumor progression and aggressiveness in GC." (PMID 36358890, 2022). "Collectively, our experimental data demonstrated that PDCD5 harbored tumor-suppressive property by inhibiting the proliferation of RCC cells and enhancing the immune functions of T cells via the HDAC3/miR-195-5p/SGK1 axis." (PMID 36266728, 2022). "It is worth noting that HDAC inhibitors can thwart M2-type polarization of GAM and retard GBM tumor growth by restricting activation of histone marks or targeting the STAT6 signaling pathway in a HDAC3-dependent manner." (PMID 35572545, 2022). "In addition, HDAC3 inhibition might show cytotoxic tumor effects." (PMID 35163049, 2022).
tumor (continued). "The first suggests that high overexpression of HDAC3 in GC cell lines induces the expression of miR-454, which targets the chromodomain helicase DNA binding protein 5 (CHD5), a reported tumor suppressor gene in various types of cancers including GC." (PMID 36358890, 2022). "HDAC3, a class I HDAC that is present in the nucleus and cytoplasm of cells, is involved in tumor development, DM, inflammation, and cardiovascular and neurodegenerative diseases." (PMID 33736642, 2021). "These preclinical experiments suggest that HDAC3-specific inhibition may be an effective therapy for GCB lymphomas, particularly those with CREBBP-mutations, by reducing the dominance of BCL6 on transcription programs and improving both terminal differentiation and immunogenicity of tumor cells." (PMID 35071240, 2021). "Clinically, the correlation analysis manifested that abnormally expressed HDAC3 was closely correlated with clinicopathological parameters of HCC, including tumor size, venous infiltration, TNM stage and Edmondson Steiner grading (P<0.05, respectively)." (PMID 34335948, 2021). "The results validated that down-regulation of HDAC3 or TGIF1, or up-regulation of miR-296-3p resulted in suppressed tumor growth, elevated apoptosis rate and inhibited TGF-β1, Smad2 and Smad3 expression." (PMID 33203425, 2020). "Therefore, HDAC3 might be a crucial epigenetic enzyme affecting the tumor immune microenvironment." (PMID 32934224, 2020). "This study illustrates that down-regulation of HDAC3 or TGIF1 or up-regulation of miR-296-3p discourages CRC cell progression and slows down tumor growth, which guides towards a novel direction of CRC treatment." (PMID 33203425, 2020). "HDAC1 (p = 0.05), HDAC3 (p = 0.02), the second probe of HDAC5 (p = 0.04) and of HDAC7 (p = 0.03), and HDAC8 (p = 0.004), were increased in tumours with 8q gain, while HDAC11 was decreased (p = 0.002)." (PMID 33316946, 2020). "After depletion of HDAC3 or TGIF1 or augment of miR-296-3p, the tumor cells were characterized by cellular shrinkage, dense chromatin in the nucleus, markedly reduced mitotic division, with scattered foci and necrotic lesions fused into sheets." (PMID 33203425, 2020). "Tumor cell proliferation is also supported by PKM2-dependent phosphorylation the Thr11 of histone H3, favoring its acetylation, and the removal of HDAC3 (histone deacetylase 3) from CYCLIN D1 and MYC promoters." (PMID 33008042, 2020). "Expression of HDAC1 (p = 0.02), HDAC3 (p = 0.04), HDAC4 (p = 0.001), as well as HDAC8 (p < 0.001) was significantly higher in M3 tumours compared to D3 tumours." (PMID 33316946, 2020). "As expected, this combined regimen increased the level of ac-histone-H3 and decreased that of phopho-HDAC3, as a result retained the level of CD20 in the tumour tissue." (PMID 31907371, 2020). "Down-regulation of HDAC3 abrogates the ability of HDAC inhibitor valproic acid (VPA) to modulate AKT phosphorylation, suppress tumor cell growth, and induce autophagy." (PMID 31024564, 2019). "Two studies found a correlation between miRNA449 down-regulation and HDAC1/HDAC3 up-regulation; two HDAC family members important for tumor cell proliferation." (PMID 30223590, 2018). "Overexpression of HDAC3 was correlated with early recurrence of HCC after surgery and advance tumor stage." (PMID 28401148, 2017).